NNMT (nicotinamide N-methyltransferase)
Diseases named in the same sentence as NNMT in open-access papers (continued):
Sharing a sentence is not in itself a finding about the gene and the disease.
tumor (continued). "Furthermore, investigating the single‐cell expression of NNMT, we observed predominant expression in tumor cells, with minimal expression detected in immune cells." (PMID 38126621, 2024). "Some scholars have speculated that other genetic changes, such as elevated N-methyltransferase (NNMT), followed by the enhancement in tumor migration and invasion, might contribute to the characteristic morphology observed with the MELF pattern." (PMID 39456648, 2024). "Nicotinamide N-methyltransferase (NNMT) is a metabolic enzyme associated with tumor-associated fibroblast (CAF) differentiation and tumor progression, low levels of NNMT inhibited p-Akt and tumor development." (PMID 37089959, 2023). "On the whole, NNMT downregulation in LIHC relieves the inhibition of fatty acid and cholesterol synthesis in tumor cells, promotes tumor progression by causing a detoxification capability loss, and reduces the consumption of SAM which makes SAM available for other crucial reactions." (PMID 35338115, 2022). "In conclusion, our findings suggest that NNMT contributes to tumor progression and may serve as a promising therapeutic target for OSCC." (PMID 36291696, 2022). "Furthermore, the expression of NNMT was related to the tumor TNM stage and a poor prognosis in iCCA tissues." (PMID 35851575, 2022). "Previous studies have mainly focused on NNMT upregulation and downregulation in whole tumor tissue." (PMID 35756670, 2022). "The NNMT gene was highly expressed in primary tumour tissue compared with normal tissue." (PMID 36118874, 2022). "Indeed, dual inhibition of NNMT (using the inhibitor NNMTi23) and glycolysis in both ccRCC cell lines (786‐O and A498) and two 2D ccRCC primary models derived from tumour (RCC2) and metastasis (RCC1) led to strongly decreased cell viability." (PMID 35678045, 2022). "In aggregate, NNMT performs a pro-tumor role in PAAD as a downstream target of aberrantly activated Hedgehog signaling, but the concrete mechanisms urgently need to be elucidated, which will aid in discovering novel therapeutics and treatments for PAAD patients." (PMID 35338115, 2022). "This research can shed light on the function of NNMT in tumor immunotherapy." (PMID 36386816, 2022). "Similarly, NNMT was more expressed in tumor tissues from 10 pairs of iCCA specimens than in paracancerous tissues." (PMID 35851575, 2022). "1-Methylnicotinamide is produced by NNMT, which is mainly expressed in tumor cells and fibroblasts." (PMID 35222522, 2021). "In addition, a negative correlation was observed between miR-449a levels and nicotinamide N-methyltransferase (NNMT) and knock-down of NNMT led to re-expression of miR-449a, inhibition of tumor growth, and activation of phosphatase and tensin homolog (PTEN)." (PMID 33809566, 2021). "Similarly to what was previously reported, NNMT expression was found to be inversely related to tumor size." (PMID 34439880, 2021). "Moreover, survival analysis found an increase of NNMT enzyme activity from non-tumor to tumor tissues (p < 0.0001) and from N0 OSCC to N+ OSCC (p < 0.0001)." (PMID 34827592, 2021). "We speculated that the depletion of NNMT promotes histone methylation and leads to tumor suppression." (PMID 34655178, 2021). "NNMT expression replicates many of the effects of these genes, such as promoting the EMT, extracellular matrix remodelling and activation of cell signalling pathways, hence NNMT-mediated changes in epigenetic regulation are likely responsible for some of its pro-tumour effects." (PMID 34680055, 2021). "The expression of NNMT is restricted to fibroblasts and tumor cells." (PMID 35222522, 2021). "The overexpression of NNMT has been shown to cause depletion of the cellular pool of SAM, distorting the SAM/SAH balance, subsequently leading to a hypomethylated state with downstream effects on gene expression associated with tumor growth and metastasis." (PMID 34572571, 2021).
tumor (continued). "Moreover, transfected and control PE/CA PJ-15 cells (5 × 106 cells) were injected into athymic BALB/c nude (nu/nu) mice to investigate the effect of NNMT downregulation on tumor growth." (PMID 34827592, 2021). "Interestingly, NNMT was overexpressed in tumor tissue, with a mean 2.39 increase of the transcripts in the OSCC tissues as compared to the normal mucosa, indicating an important role for this gene in oral carcinogenesis (p < 0.05)." (PMID 34827592, 2021). "We speculate that depletion of NNMT promotes histone methylation and leads to tumor suppression because NNMT consumes S‐adenosyl methionine (SAM), which is an essential methylation cofactor." (PMID 34655178, 2021). "In addition, NNMT is also highly expressed in several tumor types, indicating an oncogenic function." (PMID 31294922, 2019). "In our previous study, we demonstrated that NNMT downregulation resulted in significantly reduced KB cancer cell proliferation, supporting the hypothesis that the enzyme may play a role in tumor growth." (PMID 23990942, 2013). "In this regard, NNMT activity, lowering nicotinamide intracellular levels, could play an important role in both tumor cell growth and chemoresistance." (PMID 23990942, 2013). "Increased NNMT enzyme activity in tumor cell may also affect the metabolism of antineoplastic compounds." (PMID 23990942, 2013). "Moreover, we recently demonstrated that NNMT mRNA and protein levels as well as NNMT activity were increased in NSCLC samples compared with both tumor-adjacent and surrounding tissue." (PMID 23990942, 2013). "NNMT was identified as a tumor biomarker, promoting cell migration and cell invasion." (PMID 23590835, 2013). "In athymic mice, NNMT silencing induced a marked reduction in tumour volume." (PMID 23990942, 2013). "Whether the reduced NNMT expression inhibits the tumor growth and metastasis of ccRCC cells was investigated by the experiment of NOD-SCID mice." (PMID 22545051, 2012). "Thus, there's a possibility that increased NNMT expression is related to cell mobility and tumor invasiveness in high stage HCC." (PMID 19216803, 2009). "In addition, NNMT was involved in OSCC tumour cell proliferation and migration in vitro and may be considered as critical regulator of EMT in OSCC as well as a prognostic biomarker in OSCC." (PMID 40535577, 2025). "In addition, NNMT promoted OSCC tumour cell proliferation and migration in vitro." (PMID 40535577, 2025). "However, this tumor‐promoting effect was greatly abolished by KD of NNMT." (PMID 39887931, 2025). "In addition, the high expression of NNMT in these tumors positively correlates with tumor size and progression, suggesting that NNMT may regulate the initial stage of malignant transformation." (PMID 35851575, 2022). "In contrast with what was reported for the vast majority of solid neoplasms, in patients affected with HCC, NNMT expression was found to be significantly decreased in the tumor compared to non-cancerous surrounding tissue, with enzyme levels being negatively correlated with tumor stage." (PMID 36139012, 2022). "Hepatic stellate cells had upregulated NNMT expression and altered H3K27 methylation status, which affected the N6-methyladenosine (m6A) of CD44, consequently contributing to the formation of the splice variant CD44v3, which is closely related to tumor metastasis." (PMID 35756670, 2022). "Thus, NNMT plays an important role in promoting tumor growth during the progression of iCCA." (PMID 35851575, 2022). "It has been proposed that reduced expression of NNMT may precede tumor invasion." (PMID 34073600, 2021). "Furthermore, this may also influence tumor cells’ interactions with drugs through forming complexes with NMNT (Nicotinamide N-methyltransferase)." (PMID 32082080, 2020).
tumor (continued). "In combining results of bioinformatics analyses and validation assays, tumor-related genes such as NNMT, FLI1, GAS6, lncRNA CCAT1, PDCD1LG2, and CD274 may be considered as the key regulators in tumor-like transformation in response to long-time exposure of P. gingivalis." (PMID 28286742, 2017). "Moreover, it has been suggested that NNMT expression can be used as a prognostic marker for tumor." (PMID 23990942, 2013). "Moreover, stratification of patients based on tumor NNMT mRNA levels revealed that the patients who expressed higher NNMT mRNA levels tended to have a shorter overall survival (OS) time (P = 0.053) and a significantly shorter disease-free survival (DFS) time (P = 0.016)." (PMID 19216803, 2009). "Enzymes, such as Nicotinamide N-methyltransferase (NNMT), which is involved in tumor’s metabolic reprogramming, interact with methyltransferases and modify gene expression." (PMID 38542354, 2024). "In this work, we focused on nicotinamide N-methyltransferase (NNMT), a phase II metabolism enzyme which has found to be overexpressed in several malignancies, contributing to tumor progression." (PMID 38504052, 2024). "NNMT is an important enzyme that controls NAD+ and SAM levels that regulates cellular metabolism, impacting tumor malignancy." (PMID 39399490, 2024). "Immunostaining revealed high NNMT expression in the invasive tumor front showing MELF pattern, suggesting the potential of NNMT inhibitors, envisioned for metabolic disorder treatment, as effective for managing EEC." (PMID 38002025, 2023). "The depletion of S-adenosyl methionine (SAM), a methyl donor generated from methionine, by NNMT leads to lower levels of methionine, SAM, and nicotinamide, but higher levels of oxidized NAD+ in GSCs compared to differentiated tumor cells." (PMID 37298093, 2023). "From these experiments, the transcriptional regulator GLYR1 emerged as a potential link between the SAM/SAH ratio and NNMT expression, as we showed GLYR1 likely mediates the relationship between HMT levels and NNMT expression in human primary tumours." (PMID 37883365, 2023). "Lastly, cells from the combination therapy PD-1+SMI group were mainly clustered in the apoptotic branch (NNMT+ and FSTL1+ tumor cells), suggesting that PD-1 inhibitor combined with SMI induces tumor apoptosis." (PMID 37430270, 2023). "Reportedly, activated HSCs facilitate HCC invasion and migration through upregulating the expression of NNMT that alters the histone H3 methylation on 27 methylation pattern and transcriptionally activating CD44 in tumor cells." (PMID 37007125, 2023). "The results revealed that 32 genes were upregulated, while 61 genes were downregulated in both NNMT knockdown groups (NNMT-KD1 and NNMT-KD2 tumor cells)." (PMID 35884600, 2022). "In this study, we focused on the enzyme nicotinamide N-methyltransferase (NNMT), which catalyzes the N-methylation reaction of nicotinamide and whose overexpression has been reported in numerous neoplasms, including GI cancers." (PMID 36139012, 2022). "Among the five tumor cell lines, the expression of NNMT in OSCC3 was higher than human oral epithelial keratinocytes (HOK), while NNMT expression of the remaining four tumor cell lines was lower than HOK." (PMID 36291696, 2022). "Similar results were obtained in OSCC, for which NNMT upregulation was negatively correlated with the parameters pT, lymph node metastasis, pathological and histological grading; this evidence led to hypothesize its potential involvement in tumor growth and differentiation." (PMID 34638427, 2021). "SPP1, CRYAB, NNMT and HILPDA were highly expressed in tumour cells (ccRCC1); GSTA2, BHMT and ADSSL1 were highly expressed in tumour cells 1 (ccRCC2); and HIF1A-AS2, DNAH11 and EGOT were highly differentially expressed in tumour cells 2 (ccRCC2)." (PMID 34168986, 2021).
tumor (continued). "In particular, NNMT expression is higher in OSCC tissue compared to normal mucosa, while its expression seems to decrease with increasing histological grading, tumor size, lymph node metastasis, and pathological staging." (PMID 34827592, 2021). "Then, NNMT protein expressions were detected in 18 intraepithelial neoplastic samples and 177 CRC tumor samples through immunohistochemistry in our study cohort." (PMID 34539890, 2021). "Tumor tissues with low ST8SIA6-AS1 expression had high miR-125a-3p level compared to tissues with high ST8SIA6-AS1 expression, and NNMT mRNA and protein levels in the ST8SIA6-AS1-depleted group were significantly lower than those in the control group." (PMID 33363573, 2020). "It was suggested that tumor-related genes such as NNMT, FLI1, GAS6, IncRNA CCAT1, PDCD1LG2, and CD274 are key regulators in tumor-like transformation under long-time exposure to P. gingivalis." (PMID 30671195, 2019). "The exemptions, i.e. NNMT, HK2, etc., were expressed in HUH7 cells as in human HCC tissues, indicating that the well-differentiated cell lines also display tumour metabolic gene expression pattern at protein level." (PMID 30176945, 2018). "Nicotinamide N-methyltransferase (NNMT) enzyme catalyzes the N-methylation of nicotinamide and its overexpression has been reported in many neoplasms, favoring traits featuring an aggressive tumor cell phenotype." (PMID 41301471, 2025). "Taken together, these findings imply that RAC3 may serve as a tumor promoter, driving hepatocarcinogenesis and the malignancy of HCC by activating the cAMP/MAPK/Rap1 signaling pathway through NNMT." (PMID 40123831, 2025). "The study unveils the link between NNMT enzymatic activity with cell‐cycle progression, indicating that 1‐MNA may be involved in the remodeling of tumor microenvironment." (PMID 38126621, 2024). "This is the first study that highlights the involvement of NNMT in MCC, supporting the hypothesis that the enzyme could represent an interesting biomarker for treatment and detection of this kind of tumor." (PMID 38504052, 2024). "The results obtained by immunohistochemical evaluation evidenced a strong NNMT cytoplasmic expression in more than 90% of the tumor cells in the analyzed fields, while the nuclei showed no immunostaining." (PMID 38504052, 2024). "On the other hand, tumor overexpression of nicotinamide N-methyltransferase (NNMT), which converts SAM to NAD+ and 1-Methylnicotinamide, leads to increased NAD+ levels, hypomethylation, and tumor progression, highlighting that altered methionine metabolism can drive oncogenesis in multiple ways." (PMID 37842241, 2023). "We did not observe prominent stromal NNMT expression in tissue sections of either primary ccRCC or ccRCC‐derived metastasis, indicating that, in ccRCC, tumour cell expression of NNMT plays the dominant role." (PMID 35678045, 2022). "Therefore, NNMT overexpression and knockdown were induced in SW480 and HT-29 cells, respectively, and the impact on tumor cell phenotype was then evaluated." (PMID 36139012, 2022). "NNMT was expressed ubiquitously in tumor cells (TCs) and fibroblast-like cells (FLCs) but was absent in tumor-infiltrating lymphocytes (TILs)." (PMID 36291696, 2022). "This selectivity towards the inhibition of tumour rather than stem cell proliferation suggests that NNMT inhibitors are likely to be selective for tumour cells, thus reducing the possibility of deleterious off-target effects for non-tumour tissues." (PMID 34680055, 2021). "The protein Nicotinamide N-methyltransferase (NNMT) was found in both the tumor tissue and the swab, but not the Pap test fluid." (PMID 33413078, 2021). "NNMT silencing had been shown to activate tumor suppressor PP2A and inhibits tumor forming." (PMID 32047515, 2019).
tumor (continued). "Taken together, NNMT, FLI1, GAS6, lncRNA CCAT1, PDCD1LG2, and CD274, whose differential expression was confirmed, may be involved in the major mechanism of tumor-like transformation induced by chronic P. gingivalis infection." (PMID 28286742, 2017). "The study indicated that, in tumor samples from patients with recurrence, the NNMT expression was elevated while the DNMT1 expression was reduced, resulting in tumor cell resistance to oxidative phosphorylation inhibitors, thus rendering these treatments ineffective and promoting tumor relapse." (PMID 40427612, 2025). "NNMT+ and FSTL1+ tumor cells displayed significantly higher pro-apoptosis scores than anti-apoptosis score, while other subcluster cells displayed significantly higher anti-apoptosis scores than pro-apoptosis scores, suggesting that NNMT+ and FSTL1+ tumor cells may be susceptible to apoptosis." (PMID 37430270, 2023). "When we analyzed the ccRCC single-cell RNA sequencing data, NNMT expression was clearly higher in tumor cells than in other cell types but similar between the WT- and MT-VHL tumor cells (Unfortunately, GPX8 expression could not be analyzed, due to non-reliable detection in this particular dataset)." (PMID 36750850, 2023). "Moreover, upregulation of genes CLU, NNMT, and S100A6, which are known to promote RCC cell proliferation and metastasis, were found exclusively in the tumor compartment of Endo-2 and could indicate a supportive role of these cells to RCC progression." (PMID 36180422, 2022). "NNMT protein was overexpressed in primary ccRCC (p = 1.32 × 10–16) and ccRCC‐derived metastases (p = 3.92 × 10–20), irrespective of metastatic location, versus non‐tumour tissue." (PMID 35678045, 2022). "Interestingly, we showed that NNMT is also highly expressed in CRC, especial in tumor stroma, but is hardly found to be expressed in ANT, which indicated that NNMT is mainly resided in the tumor stroma of CRC." (PMID 34539890, 2021). "Even though the relationship between 5-FU resistance and NNMT expression has not been explored, it is reasonable to speculate that NNMT is involved in the resistance to 5-FU in tumor cells." (PMID 27323852, 2016). "In addition, NNMT expression is not related to grade and stage in renal clear cell carcinoma but correlates negatively with tumor size, suggesting that it may play an important role in the initial malignant conversion phase." (PMID 35756670, 2022). "For non-immune cell populations, we identified tumor cells (EPCAM and CLDN4), fibroblasts (COL3A1 and NNMT), and mesothelial cells (LRRN4 and WT1)." (PMID 36788228, 2023). "In particular, 27 paired tumor and non-tumor tissue samples from patients with OSCC were investigated to measure the levels of NNMT activity." (PMID 34827592, 2021). "Several tumor marker candidates of RCC, including nicotinamide N-methyltransferase (NNMT), L-plastin (LCP1), and non-metastatic cells 1 protein (NM23A), were identified and verified." (PMID 32992891, 2020).